OTUD5 (OTU deubiquitinase 5)
Diseases named in the same sentence as OTUD5 in open-access papers (continued):
Sharing a sentence is not in itself a finding about the gene and the disease.
gastric cancer (2 papers, 2023 to 2025). A primary or metastatic malignant neoplasm involving the stomach. "Inhibition of OTUD5 holds the potential to induce ferroptosis in gastric cancer, positioning it as a promising target for the development of drug for gastric cancer." (PMID 40070026, 2025). "Consistently, overexpression of OTUD5 promoted the proliferation, while OTUD5 depletion suppressed the proliferation of gastric cancer cells." (PMID 40070026, 2025). "Given the critical role of GPX4 in the process of ferroptosis, we extended our investigation to the impact of OTUD5 on ferroptosis in gastric cancer cells." (PMID 40070026, 2025). "To explore the physiological function of OUTD5, we knocked out the Otud5 gene in the mouse gastric cancer cell line (MFC) using CRISPR‐Cas9 and eatablished the subcutaneous tumour model." (PMID 40070026, 2025). "Collectively, these results imply that OTUD5 orchestrates ferroptosis in gastric cancer cells." (PMID 40070026, 2025). "Moreover, we evaluated the impact of OTUD5 knockout on the cell cycle of gastric cancer cells by an EdU incorporation assay, and the results revealed that OTUD5 depletion decreased the proportion of cells in S phase, indicating impaired cell proliferation." (PMID 40070026, 2025). "Furthermore, colony formation assays demonstrated the reduced proliferative capacity of gastric cancer cells upon OTUD5 depletion." (PMID 40070026, 2025). "Notably, OTUD5 overexpression, knockdown or knockout did not impact the mRNA levels of GPX4, indicating that OTUD5 upregulates GPX4 expression independently of transcriptional level in gastric cancer cells." (PMID 40070026, 2025). "Notably, the anticancer effect of OTUD5 knockout was found to be comparable to that of nutlin‐3a treatment, underscoring the potential of OTUD5 as a therapeutic target for inducing ferroptosis in gastric cancer." (PMID 40070026, 2025).
gastric cancer (continued). "However, whether OTUD5 regulates ferroptosis in gastric cancer remains poorly understood." (PMID 40070026, 2025). "OTUD5 depletion destabilizes GPX4, promotes lipid peroxidation and sensitizes gastric cancer cells to ferroptosis." (PMID 40070026, 2025). "This study reveals that OTUD5, a deubiquitinating enzyme, is a key regulator of GPX4 in gastric cancer cells." (PMID 40070026, 2025). "We further investigated the pathological correlation between OTUD5 and GPX4 in human gastric cancer." (PMID 40070026, 2025). "The identification of an inhibitor for OTUD5 could potentially lead to the suppression of GPX4, preventing the onset and progression of gastric cancer." (PMID 40070026, 2025). "This suppression leads to a decrease of OTUD5 mRNA levels, a consequent reduction of GPX4 protein levels, and an increase of LPO accumulation, ultimately resulting in ferroptosis of tumour cells and the inhibition of gastric cancer progression." (PMID 40070026, 2025). "Additionally, OTUD5 silencing and nutlin‐3a‐induced GPX4 degradation enhances the sensitivity of gastric cancer cells to ferroptosis in vivo." (PMID 40070026, 2025). "More importantly, quantitative analysis revealed a significant positive correlation between OTUD5 and GPX4 protein levels and advanced stages of gastric cancer, while the p21 protein levels showed a negative correlation with advanced stages." (PMID 40070026, 2025).
lung adenocarcinoma (2 papers, 2020). A carcinoma that arises from the lung and is characterized by the presence of malignant glandular epithelial cells. "Additionally, patients with elevated OTUD5 expression had significantly longer overall survival compared to patients bearing tumors that expressed low levels of OTUD5 transcripts in NSCLC (lung adenocarcinoma, LUAD and lung squamous cell carcinoma, LUSC), PADD, CESC, LGG, and BLCA." (PMID 32826889, 2020).
triple-negative breast carcinoma (2 papers, 2024 to 2025). An invasive breast carcinoma which is negative for expression of estrogen receptor (ER), progesterone receptor (PR), and human epidermal growth factor receptor 2 (HER2). "OTU deubiquitinase 5 (OTUD5) and USP10 can stabilize YAP1 to induce M2 polarization, subsequently increasing the metastatic capacity of triple-negative breast cancer (TNBC) and PDAC cells, respectively." (PMID 38715050, 2024). "Ovarian tumor domain-containing 5 (OTUD5) is highly expressed in triple-negative breast cancer and can affect the sensitivity of triple-negative breast cancer to paclitaxel." (PMID 40959280, 2025).
acute kidney injury (1 paper, 2023). Sudden and sustained deterioration of the kidney function characterized by decreased glomerular filtration rate, increased serum creatinine or oliguria. "Functionally, OTUD5 deletion intensifies renal tubular cell ferroptosis and exacerbates acute kidney injury, while AAV-mediated OTUD5 delivery mitigates ferroptosis and promotes renal function recovery from I/R injury." (PMID 38110369, 2023). "Here, the authors demonstrate that the OTUD5 interaction with GPX4 is key in resisting ischemia/reperfusion-induced ferroptosis in renal cells, offering a new strategy for treating acute kidney injury." (PMID 38110369, 2023).
cardiac hypertrophy (1 paper, 2023). "Meanwhile, OTUD5 overexpression reduced cardiac fibrotic areas and cardiac hypertrophy." (PMID 37552043, 2023).
cervical tumor (1 paper, 2020). "Taken together, the mRNA levels of OTUD5 in cervical tumor tissues are negatively related to tumor stage and node metastasis." (PMID 32655987, 2020). "OTUD5 was reported to affect the phosphorylation of Akt in cervical tumor cells." (PMID 32655987, 2020).
chordoma (1 paper, 2023). Chordomas are rare malignant tumors arising from embryonic remnants of the notochord in axial skeleton. "Several candidate genes, including OTUD5, CDK6, LUC7L2, IER3IP1, and HEATR3, were not linked to other chordoma dependency genes following either of these two approaches." (PMID 37024492, 2023).
chronic hepatitis B (1 paper, 2023). "Overexpression OTUD5 was observed in the cytoplasm in chronic hepatitis B liver tissues compared with HBV-negative liver tissues." (PMID 37897511, 2023).
chronic myeloid leukemia (1 paper, 2026). "Notably, targeting OTUD5 with nilotinib, an FDA-approved drug for chronic myeloid leukemia (CML), enhances the OTUD5-TIF1γ interaction, reduces the ubiquitination of TIF1γ, and exerts significant anti-metastatic effects on NSCLC cells." (PMID 42185242, 2026).
chronic pancreatitis (1 paper, 2023). A chronic inflammatory process causing damage and fibrosis of the pancreatic parenchyma. "In CD4+ T lymphocytes from chronic pancreatitis tissues, the knockdown of the transcription factor Bach2 downregulates OTUD5 expression." (PMID 37190070, 2023). "The exposure of BTB and CNC homologous 2(Bach2)-silenced CD4+ T lymphocytes to chronic pancreatitis tissue extracts leads to a decrease in OTUD5 and increased Th17 cell differentiation." (PMID 37190070, 2023).
Cornelia de Lange syndrome (1 paper, 2021). A rare syndrome characterized by low birth weight, delayed growth, intellectual disabillity, behavioral problems, and a distinctive facial appearance (thin, arched eyebrows, low set ears, small teeth, and small nose). "Amongst these OTUD5 substrates are ARID1A/B, HDAC2, and HCF1, mutations of which underlie different developmental disorders (Coffin–Siris and Cornelia de Lange syndromes, X-linked mental retardation 3) that exhibit considerable phenotypic overlap with LINKED patients." (PMID 33335288, 2021).
developmental delay (1 paper, 2021). "In the present study, three affected individuals with OTUD5 missense variants were identified who had short stature and developmental delay with distinctive facial features." (PMID 33748114, 2021).
Dyskinesia (1 paper, 2025). A movement disorder which consists of effects including diminished voluntary movements and the presence of involuntary movements. "Furthermore, OTUD5 conditional knockout in DA neurons results in more severe α‐Syn related pathology and dyskinesia after injection of α‐Syn preformed fibrils (PFF)." (PMID 39721018, 2025).
gastric tumour (1 paper, 2025). "Next, we examined the regulatory role of OTUD5 on gastric tumour growth using a mouse xenograft model." (PMID 40070026, 2025).
lentivirus infection (1 paper, 2020). Virus diseases caused by the Lentivirus genus. "Using lentivirus infection to express shRNA, we generated stable OTUD5 knockdown cells, into which the control siRNA or siRNA against TRIM25 was transfected." (PMID 32826889, 2020).
lung cancer (1 paper, 2020). A malignant neoplasm involving the lung.
myocardial infarction (1 paper, 2023). Gross necrosis of the myocardium, as a result of interruption of the blood supply to the area, as in coronary thrombosis. "In addition, we have demonstrated that OTUD5 overexpression is able to profoundly mitigate I/R‐induced ferroptosis, together with subsequent myocardial remodeling, suggesting that OTUD5 is a promising new therapeutic option for myocardial infarction patients receiving reperfusion therapy." (PMID 37552043, 2023).
Sepsis (1 paper, 2024). Sepsis is defined as life-threatening organ dysfunction caused by a dysregulated host response to infection. "Consistently, Otud5-deficient mice are less susceptible to LPS- and CLP-induced sepsis." (PMID 38605168, 2024).
tumor (21 papers, 2018 to 2025). "OTUD5 expression was significantly downregulated in HCC and NSCLC tissues compared to normal tissues, and low OTUD5 expression was associated with higher tumor grade, tumor size, and TNM stage." (PMID 41050073, 2025). "The OTUD5 gene (MIM#300713) at Xp11.23 encodes ovarian tumor (OTU) deubiquitinase 5 protein, which is a deubiquitinating enzymes (DUBs) member of the OTU family." (PMID 33748114, 2021). "Moreover, reduced expression of OTUD5 was associated with an aggressive tumor phenotype and poor prognosis, whereas elevated expression of OTUD5 was associated with extended survival for people with different cancers." (PMID 32826889, 2020). "Consistently, both OTUD5‐KO and nutlin‐3a treatment significantly increased the levels of lipid peroxidation and ROS in mouse tumours." (PMID 40070026, 2025). "OTUD5 is an important member of the OTU subfamily of cysteine proteases and has been implicated in both tumor progression and tumor suppression depending on the disease type." (PMID 40001543, 2025). "OTUD5 knockdown significantly reduced the IHC score of Ki-67 in xenograft tumour tissues (P < 0.05)." (PMID 38658981, 2024). "OTUD5 knockdown significantly reduced the IHC score of SLC38A1 in xenograft tumour tissues (P < 0.05)." (PMID 38658981, 2024). "SLC38A1 is deubiquitinated and stabilized by OTUD5 and mediates the tumour-promoting role of OTUD5 in HCC." (PMID 38658981, 2024). "To reveal the mechanism underlying the tumour-promoting role of OTUD5 in HCC, we screened the potential substrate proteins of OTUD5 using IP-MS analysis." (PMID 38658981, 2024). "OTUD5 is aberrantly expressed in cancer and is considered to be a tumor suppressor or a tumor promoter in various types of cancer." (PMID 37190070, 2023). "Augmenting the ubiquitination levels of PTEN promoted NSCLC cell growth, whereas miR-652-3p inhibition promoted the tumor-suppressing effects of the OTUD5/PTEN axis in NSCLC." (PMID 35765958, 2022). "The obtained findings revealed that OTUD5 deubiquitinated and stabilized PTEN to suppress NSCLC proliferation, invasion, and migration, and miR-652-3p serving as an upstream target of OTUD5 abolished the tumor-suppressing role of OTUD5/PTEN in NSCLC." (PMID 35765958, 2022). "In PAAD, the expressions of OTUD1 (P = 1.06E−52), YOD1 (P = 2.20E−50) and OTUD5 (P = 1.53E−45) in tumor tissues were higher than those in normal tissues." (PMID 35642058, 2022). "On the other hand, high expression of OTUD5 was associated with improved overall survival in Stage II NSCLC, further underscoring the beneficial role of OTUD5 for tumor repression in NSCLC." (PMID 35765958, 2022). "Meanwhile, OTUD5 can enhance anti-tumor and anti-viral immunity by deubiquitinating and stabilizing STING." (PMID 36085200, 2022). "This study firstly validated the anti‐tumor function of OTUD5 in NSCLC and provided new clues for the development of new NSCLC therapies." (PMID 32248621, 2020). "Consistently, the western blot analysis results demonstrated that OTUD5 was downregulated in the tumor spheres derived from the OTUD5-depleted cells." (PMID 32826889, 2020). "The results showed that the expression of OTUD5 in NSCLC tissues was significantly lower than that in corresponding non‐tumor tissues (p < .001)." (PMID 32248621, 2020). "Briefly, OTUD5 potentially inhibits tumor progression by regulating PML transcription by deubiquitinating TRIM25." (PMID 32826889, 2020). "Taken together, these findings indicated that OTUD5 displays strong tumor-suppressive properties with functional consequences in different tumor." (PMID 32826889, 2020).